MMP8 (matrix metallopeptidase 8)
Diseases named in the same sentence as MMP8 in open-access papers (continued):
Sharing a sentence is not in itself a finding about the gene and the disease.
periodontitis (continued). "Herein, we show that (a) MMP-8 had the highest accuracy to discriminate between healthy and periodontitis sites, whilst (t) MMP-8 demonstrated the best diagnostic precision in the detection of mild from severe periodontitis sites (AUC ≥ 0.80)." (PMID 34441437, 2021). "The use of (a) MMP-8 and (t) MMP-8 could represent a useful adjunctive tool for periodontitis diagnosis and severity." (PMID 34441437, 2021). "The results of the χ2 test showed a close relationship between miR-1226 expression and the probing pocket depth (P = 0.002), attachment loss (P = 0.004), plaque index (P = 0.032), bleeding index (P = 0.012), and MMP-8 concentration (P = 0.001) in patients with periodontitis." (PMID 34592963, 2021). "Its presence in GCF and other oral fluids was associated with periodontal diagnosis, classification, response to treatment, and disease severity; thereby, many studies validated MMP-8 as the most effective biomarker in GCF for periodontitis and a spectrum of systemic diseases." (PMID 34441437, 2021). "Active MMP-8 found in saliva has been used as the biomarker for point-of-care devices for periodontitis, as increases in its level is correlated with severity and status of periodontitis." (PMID 34353321, 2021). "Recent studies have shown that MMP-8 is an indicator for early periodontitis in particular." (PMID 34001101, 2021). "MMP-8 was the marker that showed the highest abundance among individuals with periodontitis." (PMID 33742017, 2021). "Consequently, MMP-8 is regarded by many studies as one of the most promising biomarkers for periodontitis in oral fluids." (PMID 34353321, 2021). "MMP-8, the main gingival collagenase, is related to the periodontal status, severity, and progression, representing the most studied biomarker for the diagnosis of periodontitis in gingival crevicular fluid." (PMID 34441437, 2021). "In addition, a significance difference was observed in the bleeding index, plaque index, and MMP-8 levels between periodontitis patients and healthy volunteers (P < 0.05)." (PMID 34592963, 2021). "Thus, increases in MMP-8 and MMP-9 levels in GCF were associated with both the severity of periodontitis and GDM development." (PMID 34769262, 2021). "Therefore, this study aimed to compare the effectiveness of propolis extract with CHX as an adjunctive treatment for periodontitis by evaluating their effect on clinical parameters and salivary levels of MMP-8." (PMID 35919679, 2021). "Finally, the correlation between total and active MMP-8 in all samples was disaggregated according to the diagnosis and periodontitis severity of the sites (H versus Ps and M versus S)." (PMID 34441437, 2021). "In addition to MMP-8, patients with severe periodontitis have been reported to have significantly higher levels of IL-1β and an elevated MMP-8/TIMP-1 molar ratio." (PMID 33916950, 2021). "Thus, we propose the use of MMP-9 and especially MMP-8 levels as biomarkers of periodontal disease during orthodontic treatment to facilitate the detection of early periodontitis or gingivitis." (PMID 33567492, 2021). "This could explain the low levels of MMP-8 among the LT recipients with advanced periodontitis, as periodontal treatment is known to lower MMP-8 levels." (PMID 33916950, 2021). "Furthermore, the mean of salivary levels of MMP-8 in the healthy group was significantly lower than those in the control and propolis groups (all periodontitis patients) at baseline (P<0.001)." (PMID 35919679, 2021). "Studies have shown that MMP-8 activity is a key sign of periodontitis." (PMID 35919679, 2021). "Moreover, lower amounts of gingivitis and periodontitis biomarker MMP-8 were seen on the treated side." (PMID 34063662, 2021). "However, these medications act as suppressors of inflammatory response, which means that both clinical and sub-clinical indices of periodontitis (i.e., bleeding on probing as well as MMP-8 expression and activation, respectively) can be restrained." (PMID 32143418, 2020).
periodontitis (continued). "This study shows that locally applied vitamin C reduces alveolar bone and attachment loss, decreases levels of CTX in serum and it also reduces AGE, IL-6, 8-OHdG, and MMP-8 immunostaining in gingival tissue in rats with experimentally induced periodontitis and diabetes." (PMID 33263670, 2020). "At baseline, the MMP-8 level was different in the two groups (CG: 128.75 ± 30.74; SG: 82.26 ± 54.41), possibly due to the selection procedure that allowed to enroll patients with different stages of periodontitis." (PMID 32932898, 2020). "The aim of this study was to assess whether MMP-8, TRAP-5, and OPG levels in GCF have diagnostic potential to discriminate between healthy patients’ mild and severe periodontitis sites." (PMID 33143325, 2020). "Therefore, it is necessary to measure all forms of MMP-8 (proMMP-8, aMMP-8, and total MMP-8) to examine the relationship between MMP-8 and the severity of periodontitis." (PMID 33066545, 2020). "Additionally, P. gingivalis and T. denticola in saliva, together with elevated levels of MMP-8 can also be a strong indicator for severe periodontitis." (PMID 33343358, 2020). "Particularly, MMP8 is considered as important biomarker for periodontitis." (PMID 32646009, 2020). "This plaque induced periodontitis leads to the release of the matrix-metalloproteinase-8 (MMP-8)." (PMID 31193352, 2019). "We selected MMP-8 because of its known role in the pathogenesis of periodontal disease and a substantial literature supporting its role as a biomarker of gingivitis and periodontitis." (PMID 31363141, 2019). "The wide range of inter-subject variability in salivary MMP-8 levels may be clinically relevant and may be useful in developing novel paradigms for biomarker analysis in periodontitis which may extend their clinical utility." (PMID 31363141, 2019). "MMP-8 levels reflect progression of periodontitis and successful treatment and, as such, MMP-8 assays may have positive predictive value for periodontal disease progression." (PMID 31363141, 2019). "Combinations of the MMP-8 biomarker and pathogens that correspond with it (such as T. denticola) may give a more accurate prediction of periodontitis as compared to a single biomarker alone." (PMID 30305812, 2018). "Abundant and noncontrolled MMP-8 expression, release, and activation together with other MMPs and proteinases are considered to cause inflammation-related tissue destruction in periodontitis and in other inflammatory diseases." (PMID 30223547, 2018). "Moreover, it is expected that further studies with larger sample size and more comprehensive study design will reveal more of this issue and yield better explanation of the intrinsic mechanism of the function of MMP-8 in periodontitis." (PMID 29587716, 2018). "However, the GCF levels of MMP-8 after therapy in the periodontitis patient was still found to be higher than a control group." (PMID 30305812, 2018). "Hence, considerable attention was paid in drawing an association between periodontitis and certain inflammatory cytokines, such as interleukin-1 (IL-1), tumor necrosis factor-α (TNF-α), and matrix metalloproteinase-8 (MMP-8)." (PMID 28662701, 2017). "Moreover, we have also noticed that patients with severe periodontitis demonstrated the highest MMP-8 level in GCF." (PMID 28757684, 2017). "Moreover, it is pointed out that the assessment of the MMP-8 levels in GCF can be an excellent indicator of the effects of the advanced periodontitis treatment." (PMID 28757684, 2017). "Mmp-8−/− mice were infected with P. gingivalis via oral lavage to induce marginal periodontitis." (PMID 29163477, 2017). "The roles of MMP‐2, MMP‐8, MMP‐9, and MMP‐12 have been analyzed with respect to the genetic polymorphisms; they may contribute to the susceptibility to periodontitis." (PMID 29744169, 2016).
periodontitis (continued). "Moreover, many molecular epidemiological studies has been conducted to investigate the association between MMP-3-1171 A5/A6, MMP-8-799 C/T, and MMP-2-753 C/T polymorphisms and periodontitis susceptibility." (PMID 27095260, 2016). "MMP-8 levels were also significantly elevated in the periodontitis group (314.1 ± 25.5 ng/mL) compared to both gingivitis (199.0 ± 29.1) and healthy (130.7 ± 14.5) subjects, although there appeared to be a greater overlap across the groups with this analytes vs. the others that were examined." (PMID 26347856, 2015). "In particular MMP8 and MMP9 in gingival fluid have been shown to be associated with periodontitis." (PMID 26656474, 2015). "MMP-8, also called neutrophil collagenase-2, is one of the major collagenases that have a major part in the destruction of connective tissue and alveolar bone in periodontitis." (PMID 26464855, 2014). "MMP-8, also called neutrophil collagenase-2, is one of the important collagenases that have a major part in the destruction of connective tissue and alveolar bone in periodontitis." (PMID 26464855, 2014). "MMP-8 appears 18-fold higher in progressing periodontitis vs. stable periodontitis." (PMID 23763842, 2013). "HNC RT may result in the progression of periodontitis by increased activities of MMP-8 and -9." (PMID 40545647, 2025). "All in all, ISM1, MMP-8 and asprosin might be potential biomarkers in periodontitis with obesity." (PMID 41063065, 2025). "Salivary MMP-8 level measurement may be a reliable method to distinguish between periodontal health and periodontal disease and also to distinguish between gingivitis and periodontitis." (PMID 39641024, 2024). "Therefore, salivary MMP-8 level measurement may be reliable for differentiating healthy periodontal cases from gingivitis or periodontitis." (PMID 39641024, 2024). "Therefore, salivary MMP-8 measurement may be reliable method for distinguishing gingivitis and periodontitis from healthy periodontium, and for distinguishing between the two different diseases." (PMID 39641024, 2024). "In addition, the inhibition of MMP-8 has been shown to reduce periodontitis." (PMID 38474009, 2024). "Thus, MMP-8 has been proposed as a biomarker for the early diagnosis in periodontitis." (PMID 36840029, 2023). "The mean value of MMP8 in the DS group with chronic periodontitis showed highly statistically significant levels of -1.34000 compared to -2.18250 in the systemically healthy group with chronic periodontitis and -3.52250 in the systemically healthy control group." (PMID 37448427, 2023). "Collagenase activity in diseased periodontal tissues is mainly contributed by MMP‐8 instead of other collagenases MMP‐1 and ‐13, and especially active MMP‐8 but not total MMP‐8 is associated with and reflects periods of active connective tissue destruction and a clinical diagnosis of periodontitis." (PMID 37877535, 2023). "Latent 70–80 kDa proforms of MMP‐8 could be detected in the samples of periodontally healthy mouths (lane 1), lower molecular size fragmented (25–35 kDa), and activated forms (40–60 kDa) in the samples from periodontitis patients (lanes 2–5)." (PMID 37877535, 2023). "Moreover, additional evidence indicates that higher GCF levels of MMP-8 may predict periodontal disease progression, and that MMP-8 can also be measured as a grading biomarker to classify disease stage and progression in periodontitis." (PMID 35268009, 2022). "MMP-14, on the other hand, could activate MMP-8 and -13 in periodontitis sites." (PMID 35163727, 2022). "The differences in correlations between the biosensor and the other salivary MMP‐8 assays in comparison between healthy, gingivitis, and periodontitis groups in the current study could be partly attributed to different specificities and sensitivities between the antibodies used in the three assays." (PMID 35304757, 2022).
periodontitis (continued). "The ROC curve showed that MMP-8, MMP-9, TIMP-1, MMP-8/TIMP-1, and MMP-9/TIMP-1 had statistically significant diagnostic accuracy, with areas under the curve (AUCs) of 0.892, 0.844, 0.920, 0.986, and 1.000, respectively, when distinguishing periodontitis from the controls." (PMID 36292174, 2022). "The present study aimed to evaluate 3 biomarkers (i.e., IL-1β, IL-6, and MMP-8) out of the 5 most promising salivary host-derived biomarkers identified by recent systematic reviews and meta-analyses as good candidates to be chosen for the early diagnosis of periodontitis." (PMID 35368315, 2022). "Therefore, MMP-8 is considered a biomarker in periodontitis." (PMID 33567492, 2021). "Salivary interleukin (IL)-1β, matrix metalloproteinase (MMP)-8, pyridinoline cross-linked carboxyterminal telopeptide of type I collagen (ICTP), and Porphyromonas gingivalis (Pg) display high prevalence in the populations of interest and are strongly related to periodontitis." (PMID 34001101, 2021). "In the second study, the SDD significantly reduced the odds of increased MMP-8 levels by 60% compared to placebo during the two-year period of study (OR 0.40, 95%CI: 0.21 to 0.77, p = 0.006) among the 128 postmenopausal women with periodontitis (64 in each group)." (PMID 32756461, 2020). "Furthermore, a chair-side MMP-8 test was indicated to effectively differentiate clinically healthy sites and gingivitis from chronic periodontitis and also effectively monitor the treatment of chronic periodontitis patients." (PMID 32650590, 2020). "Collagenase-2/neutrophil-derived collagenase (also known as MMP-8) and especially its active/activated forms, have recently been identified as major collagenolytic protease, causing irreversible soft and hard tissue destruction during peri-implantitis and periodontitis." (PMID 32344881, 2020). "Medication may also affect the level of MMP8 expressed, such as host modulation with low doses of certain drugs as an adjunct to conventional treatment(s) of periodontitis/peri-implantitis, mainly aiming to modify destructive aspects of the host inflammatory response." (PMID 33081038, 2020). "Furthermore, both analytical approaches yielded readouts which distinguished between heath, gingivitis and periodontitis, correlated identically with clinical measures of periodontal disease and recorded similar post-treatment decreases in salivary MMP-8 in periodontitis." (PMID 31363141, 2019). "This cross-sectional study compares the effectiveness of an active MMP-8 (aMMP-8) point-of-care (PoC)/chairside mouthrinse test to the conventional bleeding on probing (BOP) (cutoff 20%) test in detecting subclinical periodontitis/pre-periodontitis in Finnish adolescents." (PMID 30909530, 2019). "However, the added value of using the active form of MMP-8 could be relatively small, as our findings suggest that in general, salivary biomarkers might be redundant in periodontitis screening." (PMID 31122214, 2019). "Furthermore, a previous study also showed that myricetin decreased the mRNA expression and enzyme activity of matrix metalloproteinase-1 (MMP-1), MMP-2, and MMP-8, which were involved in the inflammatory progression in periodontitis in the human gingival fibroblasts (HGF)." (PMID 27011174, 2016). "Interestingly, elevated salivary levels of pro-inflammatory cytokines including Tumor Necrosis Factor (TNF)-α and Interleukin (IL)-1β and molecules involved in tissue degradation such as Matrix Metalloproteinase (MMP)-8 and -9 has been reported in saliva from patients with periodontitis." (PMID 26799067, 2016). "In conclusion, this meta-analysis with published data suggested that the MMP-2-753 C/T, MMP-3-1171 A5/A6, and MMP-9-1562 C/T polymorphisms were associated with periodontitis susceptibility and there is lack of association between the MMP-8-799 C/T polymorphism and periodontitis." (PMID 27095260, 2016).
periodontitis (continued). "However, the differentiation of periodontitis subjects from controls by the immunofluorometric assay (IFMA) technique has proved to be stronger than the widely used enzyme-linked immune sorbent assay (ELISA) method, based on salivary MMP-8 detection." (PMID 26464855, 2014). "Negative changes of the immune system include alterations of periodontitis-related factors, that is, reduction of anti-inflammatory IL-10 and increase of TNF-α and MMP-8 (matrix metalloproteinase 8)." (PMID 39975550, 2025). "on greater MMP‐8 in the saliva, mouth rinse, and GCF of periodontitis patients compared to control indicate the potential use of saliva as a surrogate biological fluid for the biomarker assessment instead of GCF." (PMID 38852177, 2025). "MMP-8 has been extensively studied in various biological fluids, including GCF, PISF, saliva, mouthrinse, and serum, for its relevance in periodontitis diagnosis." (PMID 41300956, 2025). "Herein, we present a strategic framework for the development of a highly responsive biosensor platform for periodontitis diagnostics, effectively mediating MIP/analyte interactions to enable the rational design of an active MMP-8 sensing system." (PMID 41149323, 2025). "This study investigated the effect of metabolic syndrome (MetS) on periodontal clinical parameters and salivary biomarkers' matrix metalloproteinase‐8 (MMP‐8) and myeloperoxidase (MPO) in patients with periodontitis." (PMID 38852177, 2025). "For example, in the OM, pathogens like Prevotella intermedia and Fusobacterium nucleatum induce the expression of MMP-1, MMP-8, and MMP-9 during periodontitis and dental caries." (PMID 40332093, 2025). "MMP-8 and MMP-9, as the main collagenolytic enzymes in saliva and gingival crevicular fluid, are responsible for collagen degradation in gingivitis and periodontitis." (PMID 39684335, 2024). "Particular MMPs, including MMP-8, MMP-9, and MMP-13, are elevated in the saliva of patients with periodontitis." (PMID 39641024, 2024). "Recently, point-of-care (POC) mouth rinse tests, such as the active MMP-8 POC test, have been incorporated into the new classification system for periodontitis." (PMID 39445112, 2024). "Similar outcomes were revealed in a study by Kubota and colleagues: in periodontitis-affected gingival tissue, the expression of MMP (MMP-1, MMP-3, and MMP-8) mRNA was higher in the diseased group than in the control group." (PMID 38474009, 2024). "Arias‐Bujanda highlighted that the salivary biomarker Hb exhibits similar sensitivity (72%) to MMP8 and IL6 for diagnosing periodontitis, with even better specificity (75% compared to 70.5% and 73%, respectively)." (PMID 39554809, 2024). "Specifically, combinations such as MMP-8 with IL-1β, IL-1β with IL-6, or MMP-8 with IL-6 correctly identified 78%–81% of patients with periodontitis and excluded 85%–88% of non-periodontitis participants." (PMID 39554809, 2024). "Biomarkers like matrix Metalloproteinase-8 (MMP-8) and Interleukin-1β (IL-1β) contemplate inflammation and destruction of tissues in periodontitis." (PMID 39238741, 2024). "The combination of MMP-8, IL-1β, IL-6, and MIP-1α has shown promise in distinguishing between gingivitis and periodontitis, although based on a smaller study sample." (PMID 39554809, 2024). "MMP-8, MMP-9, IL-1β, IL-6, and Hb have been effective salivary biomarkers for detecting periodontitis in systemically healthy individuals, while MMP-9 and IL-1β also perform well in identifying non-periodontitis conditions." (PMID 39554809, 2024). "MMP-8, one of the MMPs found in the GCF of periodontitis patients, is an indicator of periodontal inflammation." (PMID 39400083, 2024). "Increased plasma levels of IL-1β, IL-6, TNF-α, CRP, MMP-8, and MMP-9 have been observed in patients with periodontitis." (PMID 38672972, 2024).